CCR7 (C-C motif chemokine receptor 7)
Diseases named in the same sentence as CCR7 in open-access papers (continued):
Sharing a sentence is not in itself a finding about the gene and the disease.
breast cancer (continued). "To determine if CXCR4 and CCR7 heterodimerization are relevant to the development of human breast cancer, we took advantage of the proximity ligation assay (PLA), a well-established method for determining in situ protein-protein interactions." (PMID 34685420, 2021). "CCL21 inhibits tumor growth and enhances survival by CD3 T lymphocytes, particularly in cancer cells with CCR7 expression in mammary tumor-bearing mice." (PMID 34160019, 2021). "A series of twelve cancer driver gene expressions were identified to be associated with transcription factors, of which CCR7, BRD7, DDX3X, and UBE2A were upregulated in breast cancer tissues, and the others were downregulated in breast cancer tissues." (PMID 34507558, 2021). "In a mouse model for metastatic breast cancer, CCR7-negative tumor cells metastasized to the lungs, whereas CCR7-positive transferred cells metastasized to lymph nodes and grew faster." (PMID 34830848, 2021). "CCR7-mediated VEGF-C secretion by human breast cancer was dependent on protein kinase B (AKT) signaling pathway." (PMID 33668160, 2021). "Our previous results have demonstrated a link between both CXCR4 and CCR7 functional activation and the metastatic potential of breast cancer cells." (PMID 34685420, 2021). "The expression of CCR7 is shown to be upregulated in breast cancer tissue and to mediate metastasis to lymph nodes, but expression in breast cancer lines is poorly defined." (PMID 34298676, 2021). "Our observations thus provide the first clear evidence for a specific novel link between the CXCR4-CCR7 heterodimerization, CXCR4 and CCR7 function and the metastatic propensity of breast cancer cells." (PMID 34685420, 2021). "CCR7 expression was also assessed in a range of breast cancer cell lines: MDA-MB-231, MCF-7, SKBR3, T47D and 4T1." (PMID 34298676, 2021). "CCR7 has emerged as an important marker in the prediction of axillary lymph node metastasis in breast carcinomas, particularly since CCR7 over-expression correlates with larger primary tumours, deeper lymphatic invasion and poorer survival rates." (PMID 34298676, 2021). "Despite the enormous advances in our knowledge of the nature of the chemokines in breast cancer metastasis, research about the involvement of CCR7 in cancer progression is still limited." (PMID 32340161, 2020). "On the other hand, CCR7 overexpression in MMTV-PyMT-mediated breast cancer cells, injected orthotopically into FVB mice, significantly increased lymph node metastasis." (PMID 32340161, 2020). "Studies in the field of breast cancer have shown that the correlation between the expression of CCR7 and clinical pathogenicity in human breast cancer is important, including vascular invasion, lymph node metastasis and tumor grade." (PMID 32340161, 2020). "Not only does the future metastatic organ express high levels of CXCL1, but its chemokine receptors CXCR4 and CCR7 are also highly expressed in human breast cancer cells." (PMID 32079335, 2020). "In keeping with this early observation, the subsets of CD45R0+CCR7+CD8+ TN cells in the peripheral blood mononuclear cells (PBMCs) declined in breast cancer patients, with increased proportion of T cells differentiating into CD8+ TEM cells." (PMID 33061819, 2020). "The enhanced migration capability of in vitro generated breast cancer tumor and normal cell fusions is also linked to chemokine receptor CCR7 and a ligand CCL21 interaction that is associated with the migration of breast cancer cells to the lymph nodes." (PMID 32182935, 2020). "In breast cancer, it has been proved that the chemokine receptors CXCR4, CCR7, CCR6 and CXCR3 and their ligands have been associated with metastasis." (PMID 32340161, 2020). "This comprehensive review provided an insight into chemokine-mediated mechanisms performed in breast cancer cells both in vitro and in vivo, specifically CCR7; there are still important questions that remain to be answered." (PMID 32340161, 2020).
breast cancer (continued). "CCR7 and its receptors have been particularly reported to stimulate the tumorigenesis of breast cancer." (PMID 32340161, 2020). "Researchers have found that CCL21/CCR7 chemokine axis not only induced lymphangiogenesis in breast cancer, but also promoted breast cancer cells migration and metastasis." (PMID 32195260, 2020). "For verification of CCR7 and its ligands as a therapeutic target for breast cancer progression, further studies are required to illustrate their function and the mechanism of their actions involved in breast cancer progression." (PMID 32340161, 2020). "CCR7 has been reported to influence the lymph node metastasis of cervical cancer, prostate cancer cell migration, and mammary cancer cell stemness." (PMID 32733542, 2020). "Chemokine (C-C Motif) Ligand 21 (CCL21), a chemokine basically expressed by lymphatic endothelial cells, has been suggested to attract melanoma and breast cancer cells expressing its receptor Chemokine (C-C Motif) Receptor 7 (CCR7)." (PMID 31963450, 2020). "In breast cancer tissues, CCR7 has been highly expressed especially in the luminal B-type and TNBC compared to the luminal A type." (PMID 32340161, 2020). "To date, it has been reported that the expression of CXCR4, CCR7, and CCR10 was associated with breast cancer metastases." (PMID 33244467, 2020). "It is also worth mentioning that CCR7 expression was detected with similar levels in both immortalized normal breast epithelial cells (MCF10A) as well as in a highly invasive breast cancer cell line (MDA-MB-231)." (PMID 32340161, 2020). "Our analysis revealed a positive correlation between CSF-2 (GM-CSF) and IRF8, BATF3, or CCR7 in both lung and breast cancer patient cohorts." (PMID 32759497, 2020). "Findings showed that the EMT progression in breast cancer cells was controlled by the CCL19/CCR7 axis and facilitated the invasion and migration process of tumor cells by triggering several signaling pathways." (PMID 32340161, 2020). "In breast cancer, hypoxia has been shown to increase CCR7 expression through the hypoxia-inducible factor 1 (HIF-1)-mediated activation of the endothelin receptor A." (PMID 32340161, 2020). "For example, α2,3-STs have been shown to catalyze the sialylation of chemokine (C-C motif) receptor 7 (CCR7) to affect proliferation, invasion, and anoikis in breast cancer cells." (PMID 33260650, 2020). "For example, the expression of CCL19 and CCL21, ligands of CCR7, was significantly increased in lymph nodes of breast cancer patients." (PMID 32253815, 2020). "For example, CCR7 has been demonstrated as a biomarker that can predict lymph node metastases in breast cancer, and as a metastasis and prognosis indicator in patients with esophageal carcinoma." (PMID 31555130, 2019). "Retrospective studies about diverse neoplasias showed that tumor cells that express CCR7 are present in cancer of breast, colorectal and pancreas." (PMID 31011147, 2019). "Related study identifies positive correlations between the CCR7 expression and lymphatic endothelial markers in the analyzed panel of breast cancer tissues." (PMID 31555130, 2019). "In conclusion, we revealed that Curcumae radix suppresses the level of CCR7 and inhibits migration and metastasis of breast cancer cells to lung, as well as downregulates AP1 and MMP9 expression levels." (PMID 30781353, 2019). "It has been reported that lymph nodes can produce CCL21 and the interaction between CCL21 and CCR7 can regulate the directional migration to promote the lymph node metastasis of breast cancer, suggesting that CCR7 is involved in cell migration." (PMID 31217907, 2019). "Here, we demonstrated that AP1 and MMP9 expressions in breast cancer cells were positively correlated with the levels of CCR7 and the downregulation of CCR7 reduced the mRNA levels of MMP9 and AP1 complex (c-Fos and c-Jun)." (PMID 30781353, 2019).
breast cancer (continued). "It has been reported that CCR7 gene play an important role in cancer metastasis and even CCR7 has been shown as a novel biomarker that can predict lymph node metastases in breast cancer." (PMID 30781353, 2019). "For example, the chemokine receptors CXCR4 and CCR7 have been found to be involved in breast cancer metastasis, and both CXCR4 and CCR5 have been successfully used as drug targets for haematopoietic stem cell mobilization and HIV inhibition." (PMID 30497370, 2018). "Following results were obtained by comparing the CCR7 marker expression with clinicopathologic parameters of patients with breast cancer and statistical analysis of the data by MCNemar and Fisher’s exact tests." (PMID 30233771, 2018). "Materials and Methods: This case-control practical study was carried out on total mastectomy samples from 70 patients with breast cancer and tumor-adjacent normal tissue using immunohistochemistry technique to assess the expression of CCR7 marker." (PMID 30233771, 2018). "The results of our study showed that the incidence of CCR7 marker has had a significant role in breast cancer as a prognostic biomarker in metastatic lymph nodes." (PMID 30233771, 2018). "It was shown that that EP2/EP4 mediated CCR7 upregulation enhanced the migration of breast cancer cells toward lymphatic endothelial cells and to promote lymphatic invasion." (PMID 29596308, 2018). "A recent study suggested that CCL21/CCR7 chemokine axis expressed on breast cancer cells interacts with VEGFR3 present on LECs to induce tumor-dependant lymphatic vascular recruitment and thereby lymphangiogenesis in breast cancer." (PMID 29455658, 2018). "In the PM-2 K+CD14+ cell population, the percentage of M1-like macrophages that were CCR7+CD86+ was significantly lower in patients with breast cancer than in healthy controls (p < 0.0001)." (PMID 29614988, 2018). "The chemokine receptor CCR7 and its ligands CCL19 and CCL21 have been associated with metastasis, poor survival, invasion and cell migration in primary tumors and breast cancer experimental models." (PMID 28137279, 2017). "In conclusion, all findings demonstrated that CCL19/CCR7 axis regulated EMT progress in breast cancer cells and mediated the tumor cell invasion and migration process via activation of AKT signal pathway." (PMID 28378417, 2017). "To measure the influence of CCR7 siRNA on AKT pathway in breast cancer cells, we detected the p‐AKT expression by western blot." (PMID 28378417, 2017). "Knockdown of CCR7 inhibits CCL19‐induced breast cancer cell proliferation, the cell cycle, migration, invasion and EMT." (PMID 28378417, 2017). "We show for the first time that CCR7 functionally intersects with the Notch signaling pathway to regulate mammary cancer stem-like cells." (PMID 28137279, 2017). "To measure the influence of CCR7 siRNA on CCL19‐induced breast cancer cells proliferation and the cell cycle, we also examined by MTT assay and flow cytometry assay." (PMID 28378417, 2017). "Taken all together, our results demonstrated that CCR7 participated in various processes in breast cancer progress." (PMID 28378417, 2017). "We have recently shown that CCR7 regulates stem cell-like activity in primary mammary tumors in mice and humans, and sought to understand how CCR7-mediated stemness interacts with and/or is influenced by recognized stem cell-related signaling pathways." (PMID 28137279, 2017). "We recently reported that the chemokine receptor CCR7, a multi-functional regulator of breast cancer, maintains the stem-like cell population." (PMID 28137279, 2017). "In the experimental breast cancer model, CCR7 had a novel role in the stimulation of lymphangiogenesis." (PMID 28378417, 2017). "We next examined the effect of the CCR7 TM4 peptide on CCR7-dependent response in MDA-MB-231 (MDA231) human breast cancer cells and in primary human T cells." (PMID 28819198, 2017).
breast cancer (continued). "In clinical studies, the high expression of CCR7 is related with poorer prognosis and shorter survival rate 17, 18, suggesting that CCR7 was involved in the development and recurrence of breast cancer." (PMID 28378417, 2017). "Our study suggested that CCR7 mediates EMT progress via AKT pathway, which indicated that CCR7 has a key role in breast cancer progression." (PMID 28378417, 2017). "In many tumor types, including MDA-MB-231 breast cancer cells, expression of CCR7 drives metastases into lymph nodes." (PMID 28416768, 2017). "Expression of the CCL21 receptor CCR7 is also increased in breast cancer cells upon TGF‐β‐induced EMT, which facilitates breast cancer cell migration toward CCL21‐positive, draining lymphatic vessels in mice, in a DC‐like fashion." (PMID 28599100, 2017). "CCR7 promoted EMT and apoptosis via AKT pathway, which indicated that CCR7 has a key role in breast cancer development progression." (PMID 28378417, 2017). "As other cancer cells, mammary carcinoma cells are able to metastasize into lymph nodes in a process involving the CCL21/CCR7 axis." (PMID 28416768, 2017). "For another study, TGF-β1-induced EMT promotes breast cancer cell migration toward lymphatic endothelial cells by activating CCR7." (PMID 27548154, 2016). "CCL21 is constitutively expressed by the lymphatics and its receptor CCR7 is expressed by melanoma and breast cancer cells." (PMID 28036019, 2016). "In human breast cancers and esophageal SCC, causality analysis between CCR7 expression and LN metastasis has shown that CCR7 expression is significantly correlated with poor outcomes in patients." (PMID 28036019, 2016). "We demonstrated that the expression of CCL21/CCR7 by breast cancer cells has the ability to promote tumor-induced lymph-vascular recruitment in vivo." (PMID 25744065, 2015). "Prior publications reported that a majority of primary breast cancer tissues and metastatic cancer cells in the lymph nodes overexpress CCR7." (PMID 26313265, 2015). "We found that CCR7 mRNA expression in human breast cancer tissues positively correlates with the expression of lymphatic endothelial markers LYVE-1, podoplanin, Prox-1, and vascular endothelial growth factor-C (VEGF-C)." (PMID 25744065, 2015). "Our previous study demonstrated that activation of TAK1 increases CCR7 expression in breast cancer cells." (PMID 25557171, 2015). "Overall, these findings suggest that CCL21/CCR7 pair has the potential to regulate VEGF-C expression/secretion in the analyzed breast cancer cell line models." (PMID 25744065, 2015). "By utilizing CCR7 or CCL21 gene manipulated breast cancer cell implants in vivo we have shown that the analyzed chemokine pair promotes host lymphatic vessel recruitment and growth." (PMID 25744065, 2015). "In similar fashion, however, CCR7 expression by tumor cells increases the likelihood of lymphatic invasion and lymph node metastasis and correlates with metastasis in breast cancer, squamous cell carcinoma of the head and neck, and colon cancer." (PMID 26176983, 2015). "Here, we have established that CCR7 correlates with the expression of lymphatic endothelial cell markers in a panel of human breast cancer tissues as well as with the expression of the lymphangiogenic factor VEGF-C." (PMID 25744065, 2015). "In liver, lung and breast cancers, CCR7 functions with other molecules, including CCRL1, VEGF-C, COX-2 and microRNA let-7a, to regulate the metastatic activities of tumor cells." (PMID 26176983, 2015). "To characterize the role of CCL21/CCR7 in situ, we used a panel of breast cancer tissues (n = 105) collected from the primary tumor site." (PMID 25744065, 2015). "Collectively, our results suggest CCR7 as a critical target of TAK1 in the mediation of breast cancer metastasis." (PMID 25557171, 2015).
breast cancer (continued). "Therefore, the objective of the present study was to investigate whether CCL21/CCR7 signaling promotes breast cancer-associated lymphangiogenesis through CCR7-dependent stimulation of VEGF-C secretion followed by LECs activation towards the development of new lymphatic vessels." (PMID 25744065, 2015). "CCR7 has emerged as an important marker in the prediction of axillary lymph node metastasis in breast carcinomas, particularly since CCR7 over-expression correlates with larger primary tumors, deeper lymphatic invasion and poorer survival rates." (PMID 25744065, 2015). "Our previous study also showed that increase of the inflammatory enzyme cyclooxygenase-2 (COX-2) in breast cancer cells produced large amount of prostaglandin E2 (PGE2) to stimulate CCR7 expression and enhance lymph node metastasis of these cells." (PMID 24915301, 2014). "In this study, we tried to study in vivo sialylation of CCR7 by using this inhibitor and explore the potential role of sialylation on CCR7-mediated signaling in breast cancer cells." (PMID 24915301, 2014). "An elegant study demonstrates that the chemokine receptors CXCR4 and CCR7 are highly expressed in human breast cancer cells, malignant breast tumours and metastases." (PMID 24915301, 2014). "Expression of CCR7 in breast cancer, melanoma and other malignant cells was found to be associated with tumor growth, angiogenesis, invasion and lymph node metastasis." (PMID 25366136, 2014). "Studies show a majority of primary breast cancer tissues and metastatic cancer cells in the lymph nodes express CCR7, and there is significant correlation between CCR7 expression and lymph node metastasis." (PMID 24259307, 2013). "Data of Cabioglu and colleagues provided evidence that CCR7 together with CXCR4 are valid biomarkers predicting axillary lymph node metastasis in T1 breast cancer." (PMID 23667660, 2013). "Further studies to demonstrate an antimetastatic effect of the anti-CCR7 therapy in an ortothopic model of breast carcinoma with MCF7 cells are warranted." (PMID 24305507, 2013). "Synthetic let-7a decreased breast cancer cell proliferation, migration, and invasion, as well as CCR7 protein expression in MDA-MB-231 cells." (PMID 22251626, 2012). "The results suggest that CCR7 silencing has an inhibitory effect on breast cancer cell proliferation, migration, and invasion, and overexpression of let-7a has the same effect as CCR7 silencing." (PMID 22251626, 2012). "Specifically, the relative roles of CCR7 and miRNA in breast cancer metastasis were examined, and thus, the CCR7 3'UTR binding miRNA was searched by using the TargetScan prediction program." (PMID 22251626, 2012). "Chemokine receptors CXCR4 and CCR7 are highly expressed in human breast cancer cells, malignant breast tumours, and metastasis." (PMID 23905066, 2012). "When using scRNA-transfected cells, breast cancer cell migration was observed in nine of 21 zebrafish embryos, and no cell migration was observed in embryos by using synthetic let-7a or CCR7 siRNA-transfected cells." (PMID 22251626, 2012). "The effects of let-7a and CCR7 siRNA silencing on breast cancer cell migration in vivo were also confirmed by using a zebrafish embryo model." (PMID 22251626, 2012). "The results provided confirmation that CCR7 expression and the consequent breast cancer cell proliferation and motility are downregulated by let-7a." (PMID 22251626, 2012). "In the present study, we determined that let-7a suppressed breast cancer cell migration and invasion by downregulating CCR7 expression." (PMID 22251626, 2012). "C-C chemokine receptor type 7 (CCR7) plays an important role in chemotactic and metastatic responses in various cancers, including breast cancer." (PMID 22251626, 2012). "In the present study, the authors demonstrated that microRNA (miRNA) let-7a downregulates CCR7 expression and directly influences the migration and invasion of breast cancer cells." (PMID 22251626, 2012).